CLOCK (clock circadian regulator)
Diseases named in the same sentence as CLOCK in open-access papers (continued):
Sharing a sentence is not in itself a finding about the gene and the disease.
preeclampsia (3 papers, 2024 to 2025). Preeclampsia is a hypertensive disorder of pregnancy that is characterized by new-onset hypertension with proteinuria presenting after 20 weeks of gestation, and depending on mild or severe forms may initially present with severe headache, visual disturbances, and hyperreflexia. "In addition, biological rhythms and preeclampsia are linked, and ARNTL and CLOCK hub proteins are involved in circadian pathways." (PMID 38666946, 2024).
steatosis (3 papers, 2023 to 2026). Increased lipid within the cytoplasm of cells. "Cultured hepatocytes from steatotic liver treated with ghrelin show a recovery of their circadian pattern of clock genes such as BMAL1, CLOCK and PER, previously blunted by steatosis." (PMID 38792568, 2024). "In contrast to the transcript levels, CLOCK and CRY1 protein levels were lower under steatosis conditions compared to fructose treatment (p = 0.01, p = 0.005, respectively, Student’s t-test), suggesting a direct effect of the fatty acid mixture regardless of the monosaccharide." (PMID 36837757, 2023).
-CoV-2 infection (2 papers, 2021 to 2024). "The humanAce2 promoter encodes potential binding sites for BMAL1 and CLOCK(Dreos etal., 2017), consistent with a role of these circadiancomponents to regulate ACE2 expression and susceptibility toSARS-CoV-2 infection." (PMID 33480287, 2021).
allergic rhinitis (2 papers, 2018 to 2023). Inflammation of the nasal mucous membranes caused by an IgE-mediated response to external allergens. "CC1, characterized by a high expression of PER genes and low expression of CLOCK and BMAL1, had the highest prevalence of comorbid allergic rhinitis and atopic dermatitis, caused by general activation of immune-related signaling pathways." (PMID 37108640, 2023). "The present study investigates the expression level and distribution pattern of PER1, PER2, CLOCK, and BMAL1 genes in nasal mucosa of healthy controls, allergic rhinitis patients, and normal rats." (PMID 29534090, 2018).
asthma (2 papers, 2023 to 2025). "YTHDF1, identified as a significant modulator of airway inflammation in asthma, augments the translation of CLOCK in an m6A‐dependent manner." (PMID 41473388, 2025). "This enhancement of CLOCK translation by YTHDF1 is instrumental in the inflammatory process, as YTHDF1 further activates the NLRP3 inflammasome, leading to the production of IL‐1β, a key cytokine in asthma‐related airway inflammation." (PMID 41473388, 2025). "However, the deletion of CLOCK abrogates these inflammatory phenotypes, indicating the integral role of CLOCK in the YTHDF1‐mediated inflammatory response in asthma." (PMID 41473388, 2025).
autism (2 papers, 2010 to 2025). Persistent deficits in social interaction and communication and interaction as well as a markedly restricted repertoire of activity and interest as well as repetitive patterns of behavior. "In addition, NPAS2 is a close analog of CLOCK and its polymorphisms have earlier been associated with autism, a disorder characterized among others with impaired social interaction and communication." (PMID 20368993, 2010).
brain tumor (2 papers, 2022 to 2026). "Particularly, a significant correlation between CLOCK, BMLA1, and NOTCH genes, involved in brain tumor progression, appear to emphasize the risk in patients with migraine to develop brain tumor." (PMID 36556190, 2022). "In addition, CLOCK stimulates tumor spread in different brain tumor models and regulates cancer metabolism." (PMID 36556190, 2022).
colitis (2 papers, 2022 to 2025). Inflammation of the colon. "In addition, mice with induced colitis and patients with IBD also exhibit disruptions in clock gene expression (including genes encoding BMAL1, CLOCK, PER1/2, CRY1/2, NPAS2, REV‐ERBα, RORα, etc.)." (PMID 40911428, 2025).
coronary heart disease (2 papers, 2024 to 2025). "In the CORDIOPREV study, CLOCK gene variants were associated with the Mediterranean diet in patients with coronary heart disease (CHD)." (PMID 40944193, 2025). "The CORDIOPREV trial from Spain highlighted the effects of APOE and CLOCK gene variants on lipid and inflammatory outcomes in coronary heart disease (CHD) patients following Mediterranean and low-fat diets (<30% of total calories)." (PMID 40944193, 2025). "In adults with coronary heart disease, blood lipid levels were evaluated according to the genotypes of the CLOCK rs3749474, rs4580704, and rs1801260 genes." (PMID 39744380, 2024).
dementia (2 papers, 2011 to 2025). Loss of intellectual abilities interfering with an individual's social and occupational functions. "Presently, more and more data are emerging demonstrating how alterations of the CLOCK gene system might contribute to the pathophysiology of AD and other forms of dementia." (PMID 22028968, 2011). "CLOCK genes are crucially involved in the maintenance of such rhythmicity, and studies linking this molecule family to brain and body processes in Alzheimer patients can further elucidate the etiopathogenesis of this most frequent dementia." (PMID 22028968, 2011). "Furthermore, integrating genetic and epigenetic analyses—such as the role of circadian regulation genes (e.g., CLOCK and BMAL1) or APOE variations—could elucidate individual variability in sleep-dementia pathways and support the development of personalized interventions." (PMID 40214959, 2025).
diabetic retinopathy (2 papers, 2022 to 2024). "The excessive CLOCK-dependent expression of DEC2 and VEGF leads to incorrect neovascularization and in consequence diabetic retinopathy." (PMID 35054894, 2022).
endothelial dysfunction (2 papers, 2015 to 2016). In vascular diseases, endothelial dysfunction is a systemic pathological state of the endothelium (the inner lining of blood vessels) and can be broadly defined as an imbalance between vasodilating and vasoconstricting substances produced by (or acting on) the endothelium. "Our previous studies have shown that CLOCK induces Rho GTPase mediated endothelial dysfunction and NF-κB mediated inflammatory responses via production of ROS." (PMID 28058089, 2016). "CLOCK silencing attenuated the effects of hypoxia-induced autophagy and endothelial dysfunction." (PMID 28058089, 2016).
focal epilepsy (2 papers, 2018 to 2023). A seizure caused by a localized disorder. "The CLOCK protein was revealed to be significantly downregulated in the neurons of human focal epilepsy patients, and the seizure threshold was reduced in excitatory pyramidal neuron-specific Clock−/− knockout mice." (PMID 36835631, 2023). "The authors conclude that the similarities between brain tissue from Emx-Cre;Clockflox/flox mice and from epileptic patients suggest that disruption of CLOCK may be a central component of dysfunctional cortical circuits involved in the generation of focal epilepsy." (PMID 30210228, 2018).
gastric adenocarcinoma (2 papers, 2019 to 2021). "For example, in stomach adenocarcinoma, deep deletion and arm-level deletion of CLOCK give rise to a downregulated level of CD8 T cells." (PMID 31708917, 2019).
heart failure (2 papers, 2021 to 2022). Inability of the heart to pump blood at an adequate rate to meet tissue metabolic requirements. "The circadian regulation of Nampt by the repressor E4BP4 downstream of repressive REV-ERBs, mirrored by the transcriptional activating complex of BMAL1:CLOCK also regulating Nampt expression, links the common feature of decreased NAD+ in heart failure to circadian disruption and aging." (PMID 36062878, 2022). "Therefore, we further focused on Gpr68 as a CLOCK-dependent 5/6Nx-induced gene and investigated its function in CKD-induced heart failure." (PMID 33986294, 2021).
Herpes simplex infection (2 papers, 2019 to 2022). "Furthermore, the CLOCK gene was involved in the herpes simplex infection pathway and related to human disease." (PMID 31214170, 2019). "The CLOCK and USP7 genes were included in the Herpes simplex infection pathway." (PMID 31214170, 2019).
hypercortisolism (2 papers, 2020 to 2024). "This loss of circadian rhythmicity might be related to alterations in the expression of CLOCK genes, resulting in hypercortisolism and chronic inflammation, increasing the risk of chronic cardiometabolic disorders." (PMID 32775407, 2020). "The circadian rhythm of peripheral clock gene expression (CLOCK, BMAL, PER1-3, and CRY1) was abolished as a result of hypercortisolism, and that may contribute to metabolic disorders observed in Cushing patients." (PMID 38517306, 2024).
kidney cancer (2 papers, 2022 to 2023). Primary or metastatic malignant neoplasm involving the kidney. "In Wilms tumors, rare kidney cancers that primarily affects children, the expression of CLOCK protein is dramatically reduced in tumor cells, suggesting that the CC molecular axis may be disrupted in dedifferentiation-mediated embryonal tumors." (PMID 36672355, 2023). "For example, CLOCK, CRY1, and CRY2 levels were downregulated in kidney cancer tissue." (PMID 35356228, 2022).
liver cancer (2 papers, 2024 to 2025). An epithelial or non-epithelial malignant neoplasm that arises from the liver. "It normalizes the expression of circadian proteins like BMAL1 and CLOCK, which are often disrupted in liver cancer cells, aiding in the treatment of cancer." (PMID 39062777, 2024).
migraine (2 papers, 2019 to 2023). "Our exploratory study demonstrated a connection between a circadian gene variant and migraine: CLOCK rs10462028 was associated with a migraine phenotype in interaction with financial difficulties in a European cohort from Manchester and Budapest." (PMID 32038187, 2019). "In conclusion, our results show that genetic variation in the CLOCK gene is associated with migraine depending on the level of perceived financial stress." (PMID 32038187, 2019). "In the present study, we investigated the main effect of rs10462028 of the circadian locomotor output cycles kaput (CLOCK) gene and its interaction with different stress factors on migraine." (PMID 32038187, 2019). "A recent study also suggested that CLOCK regulates brain plasticity during key developmental periods and thus may contribute to several brain disorders, such as migraine." (PMID 32038187, 2019). "Recent meta-analyses of genome-wide association studies (GWASs) for migraine have not identified CLOCK as a susceptibility gene for migraine." (PMID 32038187, 2019). "However, our study did not confirm a possible interaction effect between CLOCK and CHA on migraine." (PMID 32038187, 2019).
renal carcinoma (2 papers, 2014 to 2021). A carcinoma arising from the epithelium of the renal parenchyma or the renal pelvis. "Considering the results that the Per2 circadian rhythm was shown only in Caki-2 cells, which contained BMAL1, CLOCK, and HIF1α protein, it is possible that HIF1α is related to the Per2 circadian rhythm in renal cancer cell lines." (PMID 25333958, 2014). "This suggested that both BMAL1/CLOCK and HIF1α may be related to the circadian expression of Per2 in renal cancer cell lines." (PMID 25333958, 2014). "All renal cancer cell lines expressed CLOCK and CRY1 protein, but did not express PER2 protein." (PMID 25333958, 2014).
substance abuse (2 papers, 2020 to 2024). The use of a drug for a reason other than which it was intended or in a manner or in quantities other than directed. "CLOCK is disrupted in substance abuse and mice exhibiting mutations in CLOCK are hyperdopaminergic and more susceptible to drug addiction." (PMID 32423100, 2020). "The impact of substance abuse on CLOCK gene expression seems quite evident." (PMID 39584972, 2024). "Furthermore, research into human genetics and gene expression has revealed a connection between CLOCK gene activity and substance abuse." (PMID 39584972, 2024).
temporal lobe epilepsy (2 papers, 2022 to 2025). A localization-related (focal) form of epilepsy characterized by recurrent seizures that arise from foci within the temporal lobe, most commonly from its mesial aspect. "Meanwhile, CLOCK and REV-ERBα were found to be increased in the brain tissue of patients with temporal lobe epilepsy." (PMID 40572688, 2025). "Like CLOCK and BMAL1, expression of REV-ERBα is similarly dysregulated in patients with temporal lobe epilepsy." (PMID 36161152, 2022).
thyroid cancer (2 papers, 2021 to 2023). "We found that the mRNA expression of CLOCK and BMAL1 in thyroid carcinoma tissues (PTC) was significantly higher than that in benign and normal tissues, while the expression of CRY2 was decreased, indicating that circadian biological rhythm was involved in the occurrence of the disease." (PMID 34211057, 2021). "Therefore, if it were consistently found in the reviewed studies that BMAL1, CLOCK and NPAS2 were upregulated in thyroid carcinoma, the suppressors of activity of BMAL1, CLOCK and NPAS2 (CRYs, DECs, and PERs) would be expected to be downregulated in this carcinoma." (PMID 37489438, 2023). "CLOCK and BMAL1 were dramatically expressed in thyroid carcinoma but not in benign group, while other genes were in low levels of each group." (PMID 34211057, 2021). "In the immunohistochemical experiment, the CLOCK and BMAL1 were dramatically stained in thyroid carcinoma but not in benign groups, while other genes were in low levels." (PMID 34211057, 2021).
tuberous sclerosis (2 papers, 2020 to 2025). Hereditary disease characterized by seizures, intellectual disability, developmental delay, and skin and ocular lesions. "Interestingly, the expression of the CLOCK gene in epileptic brain specimens, obtained from focal cortical dysplasia (FCD), and tuberous sclerosis complex (TSC) cases, is found to be reduced in epileptogenic tissue when compared to control tissue." (PMID 32457690, 2020).
acne (1 paper, 2025). An inflammatory process of the sebaceous glands which is characterized by comedones, nodules, papules and/or pustules on the skin. "This study suggests that circadian rhythm gene polymorphisms, particularly CLOCK rs1801260, are associated with acne risk, especially in individuals working rotating night shifts." (PMID 40705802, 2025). "This study aims to explore the relationship between MTNR1A rs2119882 and CLOCK rs1801260 variants and acne risk in Chinese occupational populations, with a focus on shift-working gas station employees." (PMID 40705802, 2025). "Binary logistic regression was used to explore the associations of different genetic models of MTNR1A rs2119882 and CLOCK rs1801260 with acne susceptibility." (PMID 40705802, 2025). "This study aimed to explore the relationship between circadian rhythm gene polymorphisms, specifically MTNR1A rs2119882 and CLOCK rs1801260, and the risk of acne in an occupational population." (PMID 40705802, 2025). "In contrast, the CLOCK rs1801260 G allele was consistently associated with increased acne susceptibility across models, with higher risk observed in night shift workers carrying AA/AG genotypes." (PMID 40705802, 2025). "Our findings revealed a robust association between the CLOCK rs1801260 polymorphism and acne susceptibility." (PMID 40705802, 2025). "Similarly, for the CLOCK rs1801260 variant, carriers of the minor genotype (AG/GG) showed significant associations with acne among rotating night shift workers under both dominant and additive models." (PMID 40705802, 2025). "Circadian disruption due to night-shift work may be aggravated in individuals carrying specific CLOCK variants, a condition linked to impaired skin barrier repair and heightened inflammation—both relevant to acne." (PMID 40705802, 2025). "Association between MTNR1A and CLOCK genes polymorphisms and acne risk among night shift workers." (PMID 40705802, 2025). "However, when analyzing the distribution of acne cases across different genotypes of the MTNR1A rs2119882 and CLOCK rs1801260 polymorphisms, individuals with the GG genotype exhibited a significantly higher acne prevalence (75%) compared to those with the AA genotype (27.4%) (p = 0.034)." (PMID 40705802, 2025). "Our findings suggest that the CLOCK rs1801260 polymorphism, particularly the GG genotype, may increase acne susceptibility—like through circadian rhythm disruption and its downstream effects on metabolic and inflammatory pathways, particularly in shift-working populations." (PMID 40705802, 2025). "However, CLOCK rs1801260 polymorphisms showed a strong association with acne susceptibility." (PMID 40705802, 2025). "Furthermore, the absence of direct circadian biomarkers, such as melatonin levels, limits the ability to definitively link between CLOCK gene variation and acne pathogenesis." (PMID 40705802, 2025). "Polymorphisms in circadian genes, such as MTNR1A rs2119882 and CLOCK s1801260, may amplify the physiological effects of circadian misalignment, leading to increased sebum production, follicular inflammation, and oxidative stress—all hallmarks of acne development." (PMID 40705802, 2025).
acute coronary syndrome (1 paper, 2020). Signs and symptoms related to acute ischemia of the myocardium secondary to coronary artery disease. "Interestingly, in patients with acute coronary syndrome, CLOCK and PAI-1 were overexpressed in peripheral blood macrophage cells, suggesting that CLOCK might play an important role in the progression of atherosclerotic plaques." (PMID 32231582, 2020).
age (1 paper, 2021). A temporal measurement of the time period elapsed since an identifiable point in the life cycle of an organism. "Our findings are consistent with early work, demonstrating that mice deficient in circadian clock proteins, such as BMAL1 and CLOCK, display age-related cataract." (PMID 34127677, 2021).
aging (1 paper, 2017). A developmental process that is a deterioration and loss of function over time. "On another note, we also observed that there was an association of cognitive aging with 3 SNPs in the CLOCK gene, particularly CLOCK rs3749473." (PMID 28412756, 2017).
Apnea (1 paper, 2021). Lack of breathing with no movement of the respiratory muscles and no exchange of air in the lungs. "Results of multivariable logistic regression analysis to examine the effects of AHR and CLOCK gene polymorphisms on caffeine therapy in apnea-free group and apneic preterm infants." (PMID 35145399, 2021).
Arrhythmia (1 paper, 2022). Any cardiac rhythm other than the normal sinus rhythm. "The additional CLOCK variant could aggravate this phenotype by increasing the reduction of the INa current, causing a high susceptibility to arrhythmias." (PMID 35231055, 2022).
arthropathy (1 paper, 2010). Any disorder of the joints. "In agreement with functional redundancy of NPAS2 and CLOCK, only double deficiency of CLOCK and NPAS2 in mice results in arthropathy (E.A. Yu and D.R. Weaver, personal communication) similar to arthropathy developed upon BMAL1 deficiency CLOCK is the major interacting partner of BMAL1." (PMID 21149897, 2010).
astrocytic tumor (1 paper, 2024). A glial tumor of the brain or spinal cord showing astrocytic differentiation. "Therefore, the methylation pattern of the CLOCK gene plays an important role in the pathogenesis of astrocytic tumors." (PMID 39001398, 2024).
Atrophy (1 paper, 2022). Any weakening or degeneration, especially through lack of use. "Conversely, the G/G allele of rs1801260 in CLOCK, where previous studies conflict on an association with evening preference chronotype, shows lowest rates of atrophy for afternoon treatment." (PMID 36130474, 2022).
bladder cancer (1 paper, 2022). "In bladder cancer tissue from human specimens, BMAL1 was downregulated, and CLOCK was upregulated, so cisplatin acts differently on both proteins through unclear mechanisms." (PMID 35356228, 2022).